ENSG00000251858
Synonyms: LOC124900349
Gene: Small nucleolar RNA gene on chromosome 14 (41,594,463 to 41,594,591, forward strand). Ensembl gene ENSG00000251858.
Gene Ontology:
Biological process: RNA processing
Cellular component: nucleolus
Homologues: Paralogues in human: SNORA31B (74% identical), SNORA31 (64% identical).